LEP (leptin)
Diseases named in the same sentence as LEP in open-access papers (continued):
Sharing a sentence is not in itself a finding about the gene and the disease.
Stroke (continued). "A casual role of leptin in CHD and stroke is not clear, although animal studies in particular have related adverse CV properties to leptin." (PMID 26035431, 2015). "In contrast, in our assessment, LEP correlated with neither TG nor HDL in stroke patients (male and female)." (PMID 26783391, 2015). "The induction of leptin expression appeared to be important factor in the inhibition of stroke lesions, whereas adiponectin was not a major regulator of blood pressure in SHRSP with genetic hypertension." (PMID 23876211, 2013). "Interestingly, in ESKD, while patients with a history of stroke presented higher leptin levels than those without a stroke history, patients with congestive heart failure showed lower leptin than those without a history of congestive heart failure." (PMID 37189644, 2023). "One study showed that a high leptin level independently predicted stroke in men but not in women." (PMID 35619087, 2022). "In a subgroup meta-analysis, a high leptin level was not independently associated with CHD in both females (OR = 1.03, 95% CI 0.86–1.23) and males (OR = 1.09, 95% CI 0.95–1.26) or with stroke in both females (OR = 1.13, 95% CI 0.87–1.47) and males (OR = 0.80, 95% CI 0.59–1.09)." (PMID 28278178, 2017). "LEP efficacy was not confirmed in stroke patients treated by rtPA." (PMID 26783391, 2015). "Our findings indicate that high leptin levels may not be associated with risks of CHD and stroke." (PMID 28278178, 2017). "Even though leptin levels and regulation seem to be closely linked to both prediction and prognosis of cerebrovascular diseases such as stroke and SAH, knowledge about circulating levels of leptin has yet not found its clinical implication." (PMID 27350906, 2016).
endometrial cancer (79 papers, 2006 to 2026). Primary or metastatic malignant neoplasm involving the endometrium (mucous membrane that lines the endometrial cavity). "Pro-inflammatory adipokines such as leptin, visfatin, and resistin are also implicated in the progression and spread of endometrial cancer cells." (PMID 39941769, 2025). "Endometrial cancer is linked to obesity and chronic inflammation, potentially mediated by adipocytokines like adiponectin, leptin, IL6, and TNFα." (PMID 40642843, 2025). "In fact, a lower adiponectin/leptin ratio, or a higher leptin/adiponectin ratio, has been linked to an increased risk of endometrial cancer." (PMID 40642843, 2025). "The same crosstalk of IL-1 and leptin was associated with greater invasiveness and chemoresistance in endometrial cancer." (PMID 39201370, 2024). "A positive correlation between leptin-circulating levels and the risk of endometrial cancer has been documented." (PMID 37509120, 2023). "Subsequent findings established that leptin signaling was implicated in promotion of endometrial cancer cell proliferation by activating STAT3 and ERK2 pathways and that leptin-induced phosphorylation of ERK2 and Akt was determined by STAT3 activation." (PMID 36674935, 2023). "Despite all these facts, it seems that the potential mechanisms involved in the association between the endometrial carcinoma and leptin are complicated and require further research in future." (PMID 37600567, 2023). "Among adipokines, leptin has been studied for its influence on endometrial cancer risk and tumor biology." (PMID 35053431, 2022). "An increased leptin-to-adiponectin ratio is associated with an increased risk of cancer, including endometrial cancer." (PMID 35628118, 2022). "Women with genotype AG of SNP -2548 G/A of leptin are less likely to be at risk for endometrial cancer given that the heterozygote AG is less frequently observed in endometrial cancer patients." (PMID 36578551, 2022). "One study conducted on 80 endometrial cancer patients showed that the expression levels of leptin and its receptor were associated with lymph node metastases and unfavorable prognosis in patients with endometrial cancer." (PMID 35053431, 2022). "A recent meta-analysis on endometrial cancer and adipocytokines has collected a host of evidence, all that point towards a positive association between leptin levels and endometrial cancer." (PMID 34951691, 2022). "In the literature, leptin levels have been positively associated with an increased risk of endometrial cancer." (PMID 35053431, 2022). "On review of the literature, adiponectin, leptin, resistin and visfatin are found to be most commonly studied in the context of endometrial cancer risk and progression." (PMID 34951691, 2022). "Lower circulating levels of adiponectin and higher levels of leptin have been associated with an increased risk for endometrial cancer." (PMID 35174651, 2022). "Various neuropeptides, consisting of hypothalamic decapeptide GnRH, neuropeptide Y, and leptin were proven to have a tight association with endometrial cancer." (PMID 35893039, 2022). "By analyzing data from tissue samples and whole blood, overexpression of leptin and its receptors was implicated in endometrial cancer both at the mRNA and protein levels." (PMID 36578551, 2022). "An elevated leptin/adiponectin ratio (L/A ratio) is associated with an increased risk of endometrial cancer in post-menopausal women and the L/A ratio seems to be a better predictor of estimated risk than either leptin or adiponectin alone." (PMID 33799622, 2021). "The expression levels of leptin and its receptor were both found to be associated with unfavorable prognosis in patients with endometrial cancer (3-year survival rate)." (PMID 33799880, 2021). "While adiponectin is inversely correlated to the progression of breast, colorectal, and endometrial cancers, leptin is associated with an increased risk of endometrial and renal cancers." (PMID 34298831, 2021).
endometrial cancer (continued). "Serum FGF21 and LEP concentrations are increased in patients with endometrial cancer, and associated with low differentiation and higher grade of tumor." (PMID 34068954, 2021). "FGF21 and FGF23 expression have been implicated in endometrial cancer due to their association with increased expression of leptin (LEP), a hormone produced in adipose tissue." (PMID 34068954, 2021). "A one-way ANOVA with the Benjamini-Hochberg correction showed that out of 38 mRNAs associated with leptin, the expression of 16 mRNAs significantly changed in endometrial cancer tissue samples compared to the control." (PMID 34202922, 2021). "The increased risk of endometrial cancer in obese women suggests that leptin secreted by adipose tissue affects the development of endometrial cancer." (PMID 34485124, 2021). "In previous study, it has been demonstrated that chemoresistance is associated with the crosstalk between leptin-induced Notch and IL-1 signaling in endometrial cancer." (PMID 33041661, 2020). "In turn, leptin added to the cell culture was associated with increasing the percentage of viable cells compared to untreated endometrial cancer cells (control)." (PMID 32531934, 2020). "In fact, as described in Ashizawa’s work, higher leptin/adiponectin ratio were significantly linked with an increased probability of developing endometrial cancer." (PMID 31052147, 2019). "A meta-analysis showed that high levels of leptin can significantly increase the risk of endometrial cancer (risk ratio, RR = 2.55) and that high levels of leptin are an independent risk factor for endometrial cancer." (PMID 31440472, 2019). "Studies recoded that the risk of endometrial cancer was associated with increased leptin or decreased adiponectin levels." (PMID 30510663, 2018). "Meta-analysis revealed a higher concentration of serum leptin in patients with endometrial cancer than in healthy controls, and the association of decreased leptin concentration with reduced risk of endometrial cancer." (PMID 30186533, 2018). "In a study on endometrial cancer specimens, the expression of leptin and Ob-R was associated with oestrogen receptor (ER) expression, lymph node metastasis, and poorer prognosis." (PMID 30510663, 2018). "The expression of leptin and its receptor were found to be associated with endometrial cancer patient's poorer prognosis (3-year survival rate)." (PMID 29682217, 2018). "Another correlation analysis also showed the positive association of leptin and leptin receptor with lymph node metastasis in endometrial cancer." (PMID 29682217, 2018). "Elevated levels of leptin are observed in obese individuals, with several studies reporting a correlation between obese individuals, high leptin levels and enhanced risk of breast, prostate and endometrial cancers." (PMID 29212170, 2017). "Clinical studies have described the association of a high leptin and a low adiponectin level in patients with endometrial cancer, and predicted a poor prognosis of these patients." (PMID 25115836, 2014). "In case-control studies, endometrial cancer has been associated with high levels of leptin and low levels of adiponectin in a Greek and Japanese population." (PMID 25115836, 2014). "Also, the serum level of leptin should be investigated and the diagnostic accuracy of leptin receptor in the endometrial cancer should be determined based on the R.O.C (Receiver Operating Characteristics) curve and the cut point." (PMID 37600567, 2023). "It has been suggested that high leptin levels are associated with prostate, colon, breast, and endometrial cancers and that leptin may play a role in this through cell proliferation via MAPK signaling." (PMID 38260162, 2023). "The previous studies have also shown that leptin has the potential to stimulate cell growth, invasion, and angiogenesis through activating different cell signaling pathways that may cause endometrial carcinoma progression." (PMID 37600567, 2023).
endometrial cancer (continued). "Additionally, a higher adiponectin‐leptin ratio (A:L ratio) has been associated with a reduced risk of endometrial cancer." (PMID 35174651, 2022). "Leptin, visfatin and resistin are linked to the stimulation of endometrial cancer growth, proliferation, invasion and metastasis and are associated with worse prognosis or with a higher grade/stage of endometrial cancer." (PMID 34951691, 2022). "Leptin-to-adiponectin ratios (L/A ratios) may be more informative in studies of the risk of endometrial cancer among postmenopausal women." (PMID 36578551, 2022). "In addition, a correlation analysis further indicated the positive association of leptin and leptin receptor levels with lymph node metastasis in endometrial cancer patients." (PMID 33799880, 2021). "For instance, leptin increases the risk of endometrial cancer, independently of the obese status of patients, indicating that leptin may be involved in the endometrial carcinogenesis by other pathways." (PMID 34202969, 2021). "Furthermore, the results of a correlation analysis in an endometrial cancer cohort demonstrated the positive association of lymph node metastasis with high leptin and leptin receptor levels." (PMID 33804101, 2021). "In addition, the expression of leptin and its receptor is associated with lymph node metastases and a worse prognosis in endometrial cancer." (PMID 33334030, 2020). "Previous studies have reported that an increase in circulating adiponectin and leptin-adiponectin ratio may be potential risk factors for breast cancer, colorectal cancer, pancreatic cancer, and endometrial cancer." (PMID 31330820, 2019). "Also in endometrial cancer, the leptin/adiponectin ratio is recognized as a more appropriate risk marker." (PMID 31052147, 2019). "Nevertheless, it has been hypothesized that leptin signalling and its crosstalk may also be associated with the more aggressive and poor prognostic type-II endometrial cancer." (PMID 30510663, 2018). "It is thought that circulating adiponectin, leptin and the adiponectin-leptin ratio may be risk factors for endometrial cancer." (PMID 27036040, 2016). "Circulating leptin levels were positively associated with endometrial cancer." (PMID 21566743, 2008). "The measurement of metabolic variability over time, such as fluctuations in body weight, insulin levels, glucose levels, leptin levels, and adiponectin levels, may provide a more accurate tool for stratifying risk of endometrial cancer than traditional static measures." (PMID 41375041, 2025). "Recent studies report that elevated leptin levels correlate with an increased risk of certain malignancies, which mainly include renal cell carcinoma, intestinal cancer, pancreatic cancer, breast cancer and gynecological cancers, including endometrial cancer and ovarian cancer." (PMID 37190027, 2023). "It was observed that leptin may promote neoplastic transformation, proliferation of cancer cells and tumor angiogenesis, indeed high levels of leptin in plasma are associated with prostate, colon, breast and endometrial cancer patients." (PMID 27029038, 2016). "Furthermore, an increase in the adiponectin-leptin ratio reduces the risk of endometrial cancer." (PMID 27036040, 2016). "The mRNA expression of adiponectin, leptin, and their receptors was analyzed in the adipose tissue of 39 patients with fresh endometrial cancer samples." (PMID 40642843, 2025). "Pro‐inflammatory adipocytokines such as leptin and IL‐6 contribute not only to cancer development but also to endometrial cancer progression through multiple mechanisms." (PMID 40642843, 2025). "The finding that higher expression of adiponectin and leptin was noted in adipose tissue compared to endometrial cancer tissue suggests their significant role in regulating adipose tissue functions and metabolism." (PMID 40642843, 2025).
endometrial cancer (continued). "In breast, colon, pancreatic, and endometrial cancers, leptin promotes proliferation by activating PI3K–Akt, JAK2–STAT3, MEK–ERK, and JNK signalling cascades." (PMID 41586225, 2025). "In prostate and endometrial cancers, leptin enhances differentiation, proliferation, and invasiveness through transcriptional upregulation of proto-oncogenes and metabolic enzymes." (PMID 41586225, 2025). "The pro-inflammatory adipocytokines leptin, visfatin, and resistin are also involved in the progression and spread of endometrial cancer cells." (PMID 38201606, 2023). "This clinical data fits well with the documented positive correlation between leptin circulating levels and endometrial cancer." (PMID 37509120, 2023). "The influence of leptin on proliferation and invasion of endometrial cancer cells depends on the dose and the rate of leptin receptor expression (Ob-R)." (PMID 37600567, 2023). "In endometrial cancer, leptin directly affects the activation of STAT3 proteins contributing to the immune escape mechanism." (PMID 37190027, 2023). "Pro-inflammatory adipocytokines, including leptin, visfatin, and resistin, play a role in the progression of endometrial cancer." (PMID 38201606, 2023). "Regarding the role of leptin in programmed cell death, the results of a study on endometrial carcinoma conducted by Zhou Chai (2015) showed leptin decreases the apoptosis in Ishikawa/ECC1 cells." (PMID 37600567, 2023). "In the multivariate regression analysis, BMI, leptin, and IL-6 were independent predictive variables of T, N, and M status in endometrioid type I endometrial cancer patients." (PMID 35053431, 2022). "Leptin-induced NILCO molecules in endometrial cancer affect cell proliferation, aggressiveness, and chemoresistance." (PMID 36578551, 2022). "In this scenario, we describe the role of leptin and adiponectin in the development of endometrial cancer." (PMID 35628118, 2022). "In studies on endometrial cancer cell lines, adiponectin has an inhibitory effect on the signalling pathways stimulated by leptin, which makes its antiproliferative and pro-apoptotic effects stronger." (PMID 35628118, 2022). "Among the type I endometrial cancer patients, the BMI and serum leptin levels were significantly higher in those patients with higher values for the T, N, and FIGO stages." (PMID 35053431, 2022). "Leptin and adiponectin are the two main adipocytokines involved in most studies in endometrial cancer." (PMID 36578551, 2022). "We obtained a significant linear correlation of leptin with BMI in both the type I and II endometrial cancer patients." (PMID 35053431, 2022). "In this study, we found a correlation between leptin levels, BMI, and the standard prognostic factors for endometrial cancer." (PMID 35053431, 2022). "Specifically, increased leptin levels were found in type I endometrial cancer patients in comparison with type II endometrial cancer patients; furthermore, leptin was correlated with T, N, and M (stage of disease) in the type I endometrial cancer patients." (PMID 35053431, 2022). "Leptin is involved in endometrial cancer by controlling energy homeostasis and increasing glycolytic capacity." (PMID 36578551, 2022). "We found that BMI, leptin, and IL-6 significantly correlated with T status, N status, and M status among endometrioid type I endometrial cancer patients." (PMID 35053431, 2022). "Taken together, these studies indicated the complex crosstalk among Notch, IL-1, and leptin as well as the involvement of IL-1 in inducing inflammatory progression and upregulating leptin expression in endometrial cancer." (PMID 36578551, 2022). "The role of leptin was more prominent in the more malignant phenotype, such as the more aggressive and poorly differentiated An3CA endometrial cancer cell line." (PMID 36578551, 2022). "The multivariate regression analysis showed that BMI, leptin, and IL-6 were predictive for T, N, and M status in the type I endometrial cancer patients." (PMID 35053431, 2022).